PTX3 (pentraxin 3)
Diseases named in the same sentence as PTX3 in open-access papers (continued):
Sharing a sentence is not in itself a finding about the gene and the disease.
renal carcinoma (4 papers, 2020 to 2026). A carcinoma arising from the epithelium of the renal parenchyma or the renal pelvis. "PTX-3 can also be useful as a non-invasive serum biomarker for diagnosing and anticipating prognosis of renal cancer." (PMID 36499628, 2022). "For instance, PTX3 increased levels in serum and biopsies of prostate and renal cancer patients reflected the attempt of a reparative process aimed to counteract systemic inflammation or the DDR-mediated genetic instability that accelerates carcinogenesis." (PMID 34572075, 2021). "We showed for the first time an increased expression of PTX3 on both renal cancer cells and ccRCC-derived tissues." (PMID 32345771, 2020). "In this context, the close relationship between PTX3 overexpression, tumour microenvironment modulation and complement cascade activation may represent an interesting pathogenic mechanisms, although experimental data on the activation of the complement cascade in renal cancer are limited." (PMID 32345771, 2020). "Noteworthy, three different renal cancer cell lines showed significantly higher PTX3 expression, as compared by PTEC." (PMID 32345771, 2020). "Remarkably, the expression of CD59, C3aR and C5aR co-localized with PTX3 expression within the renal cancer tissue samples (respectively)." (PMID 32345771, 2020). "In the attempt to validate the role of PTX3 as a potential biomarker of renal cancer, we retrospectively investigated baseline serum levels of PTX3 in a cohort of 168 consecutive patients undergoing nephrectomy for ccRCC." (PMID 32345771, 2020). "The results of the present study suggest that serum concentration of PTX3, a recognized modulator of complement system cascade, might represent a reliable non-invasive biomarker for the diagnosis and prognosis of renal cancer." (PMID 32345771, 2020).
soft tissue sarcoma (4 papers, 2018 to 2020). A malignant neoplasm arising from muscle tissue, adipose tissue, blood vessels, fibrous tissue, or other supportive tissues excluding the bones. "The soluble pattern recognition receptor long pentraxin-3 (PTX3) is an extrinsic oncosuppressor whose expression is reduced in different tumor types, including soft tissue sarcomas, via hypermethylation of its gene promoter." (PMID 30443492, 2018). "PTX3 has been described as a potent FGF2 inhibitor and has been reported to be down-modulated in different types of cancer, including soft tissue sarcomas in which its absence exerts pro-tumor effects." (PMID 30443492, 2018). "However, no data are available on the possible correlation among PTX3 expression, tumor growth, angiogenesis, and immune infiltrate in regulating soft tissue sarcomas." (PMID 31533326, 2019).
Thrombocytopenia (4 papers, 2016 to 2025). A reduction in the number of circulating thrombocytes. "These are all possible mechanisms linking together PTX3, coagulation activation, and thrombocytopenia." (PMID 34452419, 2021). "High PTX3 level associates with a clinically severe course of the disease, especially severe AKI, thrombocytopenia, and longer hospitalization." (PMID 35062248, 2021). "High PTX-3 levels during acute NE associate with a severe outcome of the disease, especially severe AKI, thrombocytopenia, and a longer hospitalization." (PMID 34452419, 2021). "Most of all, a high PTX3 level predicts significant thrombocytopenia." (PMID 35062248, 2021). "Interestingly, however, the in vivo administration of PTX3 attenuated extracellular histones-mediated cytotoxicity, but did not suppress histone-mediated thrombocytopenia." (PMID 27656184, 2016).
triple-negative breast carcinoma (4 papers, 2022 to 2024). An invasive breast carcinoma which is negative for expression of estrogen receptor (ER), progesterone receptor (PR), and human epidermal growth factor receptor 2 (HER2). "We recently identified CD44, a nonkinase transmembrane glycoprotein, as a receptor that directly binds PTX3 and mediates PTX3-induced protumor effects in triple-negative breast cancer." (PMID 38243273, 2024). "In triple-negative breast cancer cells, PTX3 inhibition led to less aggressive tumor behavior through the TLR4 signaling pathway." (PMID 39594709, 2024). "Our study provides a rationale for targeting the PTX3-mediated NF-κB by PARPi, as part of a novel therapeutic approach for triple negative breast cancer." (PMID 36555812, 2022).
ventilator-associated pneumonia (4 papers, 2014 to 2024). Serious INFLAMMATION of the LUNG in patients who required the use of PULMONARY VENTILATOR. "Finally, the PTX3 threshold of >16.43 ng/mL provided a specificity of 74.0% and a sensitivity of 68.6% for the diagnosis of ventilator-associated pneumonia (VAP)." (PMID 25530683, 2014). "Subgroup analyses showed that the area under the SROC curve of pentraxin 3 in diagnosis of ventilator-associated pneumonia (VAP) was 0.89." (PMID 32243370, 2020). "The main purpose of this study was to investigate the dynamics of pentraxin 3 (PTX3) compared with procalcitonin (PCT) and C-reactive protein (CRP) in patients with suspicion of ventilator-associated pneumonia (VAP)." (PMID 29861799, 2018).
acute pancreatitis (3 papers, 2019 to 2022). An acute inflammatory process that leads to necrosis of the pancreatic parenchyma. "The aim of this study was to further elucidate the role of PTX3 as a diagnostic and prognostic marker in acute pancreatitis (AP), a potentially strong inflammatory disease, and compare it to CRP." (PMID 31798002, 2019).
alcohol abuse (3 papers, 2011 to 2014). The use of alcoholic beverages to excess, either on individual occasions ("binge drinking") or as a regular practice. "Of chronic conditions, alcohol abusers had higher PTX3 values compared to patients without a history of alcohol abuse (maximum values 1 to 4 after blood culture 12.6 ng/ml compared to 7.3 ng/ml, p = 0.036, respectively)." (PMID 21423699, 2011).
allergic disease (3 papers, 2017 to 2022). An immune response that occurs following re-exposure to an innocuous antigen, and that requires the presence of existing antibodies against that antigen. "In this study, we demonstrated that increased shrimp allergy severity is associated with an elevated PTX3 level in the serum." (PMID 36530573, 2022). "Altogether, the results demonstrated the novel role of PTX3 in regulating the IgE-mediated inflammation of DNP- or shrimp-induced allergy in mast cells." (PMID 36530573, 2022). "Herein, our study is the first evidence to link and evaluate the involvement of PTX3 in shrimp allergy." (PMID 36530573, 2022). "Our data provide new insight to demonstrate that PTX3 is a cause of allergic inflammation and that RI37 can serve as a therapeutic agent in shrimp allergy." (PMID 36530573, 2022). "The results prompted us to further examine whether CEBPD is activated by PTX3 and contributes to shrimp allergy." (PMID 36530573, 2022). "Our data provide the first evidence that PTX3 is activated and contributes to shrimp allergy." (PMID 36530573, 2022). "However, the role of PTX3 in the development of immediate IgE-mediated shrimp allergy remains unknown." (PMID 36530573, 2022). "However, the effect of PTX3 administration was firstly evaluated in the context of allergic disease in our study, and the results showed that intranasal administration of rPTX3 significantly enhanced airway inflammation in both eosinophilic and neutrophilic asthma models." (PMID 32938460, 2020). "Thus, our data imply that PTX3 might play an important role in the allergy to shrimp." (PMID 36530573, 2022). "In addition, we showed that, upon PTX3 treatment, CEBPD is activated in mast cells and participates in shrimp allergy." (PMID 36530573, 2022). "However, the exact role of PTX3 in allergic disease context has not been fully elucidated." (PMID 32938460, 2020). "Surprisingly, the PTX3 concentration was still significantly high in the serum during the hypersensitization phase in Cebpd−/− mice, implying that PTX3 may not be regulated by CEBPD in shrimp allergy." (PMID 36530573, 2022).
ANCA-associated vasculitis (3 papers, 2025). "Clinical and preclinical data suggest that anti-PTX3 antibodies have anti-inflammatory and immunomodulatory effects in SLE, and ANCA-associated vasculitis (AAV)." (PMID 39340807, 2025).
anemia (3 papers, 2018 to 2021). A reduction in the number of red blood cells, the amount of hemoglobin, and/or the volume of packed red blood cells. "In addition, PTX3 serum levels directly correlate with the major extraintestinal manifestation such as anemia." (PMID 30013746, 2018). "We did not identify any significant differences in serum PTX3 levels in relation to clinical symptoms with exception of anemia (p<0.001)." (PMID 30013746, 2018).
aneurysm (3 papers, 2019 to 2022). Bulging or ballooning in an area of an artery secondary to arterial wall weakening. "Although the study was not performed in thoracic aneurysms, it illustrates a potential involvement of PTX3 in the pathogenesis of human aneurysm development." (PMID 36606286, 2022). "Microvascular density was related to inflammatory cell infiltrates, PTX3 expression, hypoxia and average size of aneurysms." (PMID 31703088, 2019). "Intragroup analysis for group 2 showed increased Pecam-1, CXCL8, resistin, osteopontin and decreased levels of leptin, pentraxin-3 in KD with aneurysms as compared to patients without CAA (non-significant)." (PMID 36096831, 2022). "The PTX3 expression in our tissue samples also did not correlate with aneurysm diameter." (PMID 31703088, 2019). "Intragroup analysis for group 3 patients revealed elevated VEGF-A, CXCL8, Leptin, Pentraxin-3, resistin in patients with CAA as compared to KD without aneurysms while pecam-1, endoglin and osteopontin were comparable in both." (PMID 36096831, 2022).
atrial fibrillation (3 papers, 2022 to 2025). A disorder characterized by an electrocardiographic finding of a supraventricular arrhythmia characterized by the replacement of consistent P waves by rapid oscillations or fibrillatory waves that vary in size, shape and timing and are accompanied by an irregular ventricular response. "In multivariate analyses, PTX-3 was negatively associated with BMI while it was positively associated with atrial fibrillation, sST2 levels, and C-reactive protein." (PMID 38397422, 2024).
bacterial pneumonia (3 papers, 2014 to 2025). Acute infection of the lung parenchyma caused by bacteria (e.g., Streptococcus pneumoniae, Haemophilus influenzae, Chlamydia pneumoniae, Mycoplasma pneumoniae, and Legionella pneumophila). "A possibly higher diagnostic accuracy of PTX3 levels in BAL fluid in comparison to other biomarkers was confirmed in the post hoc analysis of proven bacterial pneumonia cases." (PMID 25314919, 2014). "A new cutoff level of PTX3 levels ≥7 ng/ml in BAL fluid (identified by Youden index) was associated with 75% sensitivity, 88% specificity, 56% PPV and 94% NPV for confirmed bacterial pneumonia." (PMID 25314919, 2014).
benign prostatic hyperplasia (3 papers, 2021 to 2025). A non-cancerous nodular enlargement of the prostate gland. "They further found both increased PTX-3 tissue expressions and serum concentrations in individuals who developed cancer in comparison with those diagnosed with prostatitis or benign prostatic hyperplasia." (PMID 36499628, 2022).
brain injury (3 papers, 2021 to 2024). Acute and chronic (see also brain INJURIES, CHRONIC) injuries to the brain, including the cerebral hemispheres, CEREBELLUM, and brain STEM. "In a different preclinical study, it was demonstrated that recombinant PTX-3 administration after traumatic brain injury in mice provided activation of A2 astrocytes and improved neuronal survival and neurogenesis." (PMID 38510866, 2024). "PTX3 has been shown to promote neuroprotection, neurogenesis, and angiogenesis after ischemic brain injury." (PMID 35656007, 2022). "Additional studies have shown that PTX3 treatment after traumatic brain injury can activate the beneficial type 2 astrocytes, enhance neuroprotection and neurogenesis, and improve functional recovery." (PMID 35656007, 2022).
breast tumor (3 papers, 2014 to 2025). "Ptx3 inhibits dihydrotestosterone- and Fgf8b-driven angiogenesis and proliferation of androgen-regulated mouse breast tumor cells." (PMID 41479916, 2025).
cardiomyopathy (3 papers, 2020 to 2025). A disease of the heart muscle or myocardium proper. "The evidence for a regulatory role in the pathogenesis of dystrophic cardiomyopathy provides further incentive to the assessment of the clinical relevance of PTX3 measurement in prognostic value and in guiding therapy for cardiomyopathy of DMD." (PMID 32508664, 2020). "Dystrophic cardiac expression of PTX3 correlated positively with age and inflammatory/fibrotic pathways, suggesting that cardiac levels of PTX3 have prognostic value and potential in guiding therapy for cardiomyopathy of DMD." (PMID 32508664, 2020). "Taking into account the critical role of PTX3 in the inflammatory/fibrotic pathways and the absence of predictor markers of cardiomyopathy in DMD patients, we argued to investigate the role of PTX3 in myocardial damage and fibrosis of the mdx mouse model for DMD." (PMID 32508664, 2020).
chronic hepatitis B (3 papers, 2020 to 2025). "In conclusion, in our study, we observed that the immunoreactivities of PODXL, PTX3, and ISM1 in liver tissue were increased in fibrotic livers associated with chronic hepatitis B, compared to liver tissues with normal or low-grade fibrosis." (PMID 41462970, 2025). "In our study, the immunoreactivities of Podocalyxin, Isthmin-1, and Pentraxin-3 in the liver tissues of patients with chronic hepatitis B and high-grade fibrosis were found to be increased compared to those with low-grade fibrosis and the control group." (PMID 41462970, 2025). "PTX-3 can also be useful to differentiate chronic hepatitis B infections of early cancer, with a cut-off value of 9.231 ng/mL (79.4% sensitivity and 89.9% specificity)." (PMID 36499628, 2022). "We aimed to evaluate the immunoreactivities of podocalyxin, Isthmin-1, and pentraxin-3 in the liver tissue of patients with chronic hepatitis B. Materials and Methods: Power analysis was performed (effect size (f = 0.5), (α) = 0.05 and statistical power of 0.80)." (PMID 41462970, 2025).
chronic hepatitis C (3 papers, 2019 to 2023). "In conclusion, we assessed the PTX3 for detection of clinical significant and advanced fibrosis in patients with chronic hepatitis C. PTX3 proved useful as single diagnostic marker." (PMID 31061822, 2019).
chronic pancreatitis (3 papers, 2021 to 2022). A chronic inflammatory process causing damage and fibrosis of the pancreatic parenchyma. "In summary, serum PTX3 is potentially a sensitive and specific diagnostic biomarker for PDAC with the ability to separate PDAC from other pancreatic diseases such as IPMN and chronic pancreatitis, which pose frequent diagnostic dilemmas in clinical practice." (PMID 34188166, 2021). "Moreover, patients with PDAC have significantly higher serum PTX3 levels than those with intra-ductal papillary mucinous neoplasm (IPMN) (n = 54) or chronic pancreatitis (n = 31), common confounders in clinical practice." (PMID 34188166, 2021). "The circulating levels of LAMC2 were significantly higher in patients with cystadenoma and chronic pancreatitis than in healthy donors, and PTX3—but not LAMC2—was detected in patients with IPMN." (PMID 35681634, 2022).
coagulopathy (3 papers, 2021 to 2023). "The results showed that in those patients that presented D-dimmer levels ≥ 1 mg/L, PTX3 levels significantly and positively correlated with the occurrence of coagulopathies and the COVID-19 disease severity." (PMID 37408184, 2023). "These seven markers were: Pentraxin-3 (‘disturbed vasculogenesis’), VCAM-1 and ICAM-1 (both EC Activation), Thrombomodulin (‘coagulopathy’), MCP-1, IP-10 and VEGF (all ‘disturbed angiogenesis’)." (PMID 37194071, 2023).
Cognitive impairment (3 papers, 2024 to 2026). Abnormal cognition is characterized by deficits in thinking, reasoning, or remembering. "Using a mouse model of nicotine withdrawal (WD), we identified an activity-dependent NEPAS-pentraxin-3 (PTX3) axis in mPFC neurons that couples circuit hypoactivity to cognitive deficits." (PMID 41944308, 2026).
coronary atherosclerosis (3 papers, 2016 to 2025). Atherosclerosis of the coronary vasculature. "Recent studies have highlighted the roles of galectin-3 and pentraxin-3 as potential biomarkers in coronary atherosclerosis, yet their specific interactions and implications in patients with CCS and AF remain underexplored." (PMID 40430046, 2025). "Recently, it was reported that 50% of PTX3-positive macrophages in coronary atherosclerosis were M2 type." (PMID 28955836, 2016). "Thus, considering the function of PTX3 in control pro-inflammatory molecules production by macrophages, half of macrophages positive for PTX3 in coronary atherosclerosis presented M2-like phenotype." (PMID 31354697, 2019).
diabetic retinopathy (3 papers, 2016 to 2025). "Finally, during 2016 Zhou and Hu suggest that the use of PTX3 could be used as an anti-angiogenic molecule because PTX3 interacts specifically with FGF2 factor reducing the proliferative diabetic retinopathy thus ameliorating DR condition." (PMID 27559355, 2016). "PTX3 has been evaluated also in the retinal vein occlusion (RVO), the second most common retinal vascular disease after diabetic retinopathy." (PMID 27559355, 2016).
gastric adenocarcinoma (3 papers, 2021 to 2023). "The authors explained their reports by the assumption that they were connected to a deficiency or suppression of PTX3, which behaves as an oncosuppressor; for this reason, it can play a role in the development of gastric adenocarcinoma." (PMID 38136377, 2023). "We think that a deficit in or suppression of PTX3, which behaves as an oncosuppressor, can play a role in the development of gastric adenocarcinoma." (PMID 34048179, 2021). "Serum PTX3, IL-8 and VEGF levels decreased in cases of gastric adenocarcinoma compared to the control group, and their levels affected one another." (PMID 34048179, 2021). "Correlation tests in the present study, irrespective of groups, show that serum PTX3, IL-8 and VEGF affect one another in gastric adenocarcinomas." (PMID 34048179, 2021). "In addition, correlation tests, irrespective of groups, showed that serum PTX3, IL-8, and VEGF affected one another in gastric adenocarcinomas." (PMID 38136377, 2023).
glomerulonephritis (3 papers, 2011 to 2016). A renal disorder characterized by damage in the glomeruli. "On the other hand, IgM anti-dsDNA antibodies seem to be a protective factor for glomerulonephritis development, likewise IgG anti-pentraxin 3 antibodies, both in animal models and in SLE patients." (PMID 23951169, 2013).
infarction (3 papers, 2010 to 2025). A localised pathological necrosis of tissue resulting from obstruction of the blood supply usually by a thrombus, an embolus, or vascular torsion. "Accordingly, in the current study we found that PTX3, IL-6 and hs-CRP arecorrelated with markers of myocardial necrosis during the first 12 hours ofmyocardial infarction." (PMID 32403934, 2020).
intra-amniotic infection (3 papers, 2018 to 2023). "In line with the known biological role and site of production of PTX3, previous studies on AF derived from women with PPROM/PTL showed that elevated AF concentrations of PTX3 are associated with IAI and histological chorioamnionitis." (PMID 35536791, 2022). "The innate immune response to intra-amniotic infection and inflammation may involve the gene pentraxin 3 (PTX3)." (PMID 36669036, 2023). "The gene PTX3 may involve in the innate immune response against intra-amniotic infection and inflammation." (PMID 29755506, 2018).